CERS2 (ceramide synthase 2)
Description:
Ceramide synthase that catalyzes the transfer of the acyl chain from acyl-CoA to a sphingoid base, with high selectivity toward very-long-chain fatty acyl-CoA (chain length C22-C27). N-acylates sphinganine and sphingosine bases to form dihydroceramides and ceramides in de novo synthesis and salvage pathways, respectively (By similarity). Plays a non-redundant role in the synthesis of ceramides with very-long-chain fatty acids in kidney, liver and brain. Regulates the abundance of myelin-specific sphingolipids galactosylceramide and sulfatide that affects myelin sheath architecture and motor neuron functions (By similarity).
Synonyms: LASS2; TMSG1; SP260; FLJ10243; L3
Tractability: Antibody: UniProt predicts a signal peptide or a membrane-spanning region. PROTAC: ubiquitination databases record sites on it; its protein half-life has been measured; a small molecule that binds it is known.
Target class: Enzyme; Transferase
Gene: Protein-coding gene on chromosome 1 (150,960,583 to 150,977,396, reverse strand). Ensembl gene ENSG00000143418.
Subcellular location: Endoplasmic reticulum membrane
Subcellular location (Human Protein Atlas): Endoplasmic reticulum; Nuclear membrane
Pathways (Reactome):
Metabolism: Sphingolipid de novo biosynthesis
Gene Ontology:
Molecular function: protein binding; sphingosine N-acyltransferase activity; acyltransferase activity, transferring groups other than amino-acyl groups; DNA binding
Biological process: ceramide biosynthetic process; glycosphingolipid biosynthetic process; negative regulation of axon regeneration; negative regulation of Schwann cell migration; negative regulation of Schwann cell proliferation; regulation of lipid metabolic process; sphingolipid biosynthetic process; gene expression; response to wounding; sphingolipid metabolic process; vesicle budding from membrane
Cellular component: cytoplasmic side of endoplasmic reticulum membrane; endoplasmic reticulum; endoplasmic reticulum membrane; membrane; nuclear membrane
Genetic constraint (gnomAD): Loss-of-function variants: 20 observed, 57.97 expected, observed/expected ratio (o/e) 0.34, 90% interval 0.24 to 0.5. The upper end of that interval is the gene's LOEUF score, 0.5, which puts it in group 2 of 6, group 1 being the genes least tolerant of losing a copy. Missense variants: 357 observed, 501.87 expected, observed/expected ratio (o/e) 0.71, 90% interval 0.65 to 0.78. Synonymous variants: 186 observed, 179.73 expected, observed/expected ratio (o/e) 1.03, 90% interval 0.92 to 1.17.
Homologues: Orthologues: chimpanzee CERS2 (100% identical), macaque CERS2 (99% identical), dog CERS2 (98% identical), pig CERS2 (97% identical), rabbit CERS2 (97% identical), guinea pig CERS2 (94% identical), mouse Cers2 (92% identical), rat Cers2 (81% identical), tropical clawed frog cers2 (73% identical), zebrafish cers2a (66% identical), zebrafish cers2b (64% identical), Drosophila melanogaster schlank (38% identical), and 2 more. Paralogues in human: CERS3 (52% identical), CERS4 (47% identical), CERS5 (43% identical), CERS6 (42% identical), CERS1 (24% identical).
Diseases named in the same sentence as CERS2 in open-access papers:
CERS2 is named in the same sentence as 111 diseases in open-access papers, as found by Europe PMC text mining. Sharing a sentence is not in itself a finding about the gene and the disease. The quoted sentences say what the papers report.
breast cancer (23 papers, 2015 to 2024). A primary or metastatic malignant neoplasm involving the breast. "CerS2 overexpression in MDA-MB-231 breast cancer cells was shown to decrease cell migration and invasion, and CerS2 expression was associated with improved patient survival in breast, ovarian, lung, and liver cancer." (PMID 34069611, 2021). "Particularly, the mammary tumor tissue showed high levels of C16:0-Cer, C24:1-Cer and C24:0-Cer in comparison with non-tumoral tissue, and this increase was associated with higher expression of ceramide synthases CerS2, CerS4 and CerS6." (PMID 30149660, 2018). "In human breast cancer, the mRNA expression levels of CERS2, CERS4, and CERS6 and their respective products, C16-, C24-, and C24:1-ceramides, are increased." (PMID 37885013, 2023). "Among different breast cancer cell lines, BT-474 cells showed the lowest CERS2 expression arising from full-length PC transcript." (PMID 33568634, 2021). "CERS2 is a ceramide synthase and suppresses breast tumor cell invasion and enhances chemosensitivity of breast cancer cells." (PMID 33558504, 2021). "Overexpression of CerS-2 can significantly inhibit the migration and invasion ability of breast cancer cells, whereas knockdown CerS-2 can significantly increase the migration and invasion ability." (PMID 30988071, 2019). "The mRNA and protein expression levels of CerS-2 in poorly invasive breast cancer cells were obviously higher than that in the highly invasive cells." (PMID 30988071, 2019). "Other studies have identified a correlation between CERS2 expression with the degree of recurrence and invasion in liver cancer, breast cancer, cervical cancer, pancreatic cancer, ovarian cancer, prostate cancer, and bladder cancer." (PMID 31636736, 2019). "For instance, the presence of high levels of ceramides and their producing enzymes (CerS2) leads to a decrease in the secretion and activity of metalloproteinases, resulting in poorly invasive phenotypes of breast cancer cell lines." (PMID 30149660, 2018). "In addition, alternative splicing of CerS2 in LumB breast cancer promotes cancer cell proliferation and migration and is associated with poor prognosis." (PMID 37885013, 2023). "However, various reports and datasets from cancer patients show an increase in CERS2 in BC, ovarian, or breast cancer." (PMID 37958652, 2023). "Similarly, AGPAT9 was showed to inhibit proliferation, migration, and invasion in breast cancer by inhibiting the V-ATPase activity through up-regulating the mRNA and protein levels of CerS-2." (PMID 30988071, 2019). "It was found that CerS-2 is heterogeneously expressed in various breast cancer cells." (PMID 30988071, 2019). "In another motif combination predicted in both breast cancer and colorectal cancer, KLF6 and SP1, these two TFs together initiate the transcription of CERS2 in human prostate carcinoma cells." (PMID 28684851, 2017). "The AS signature for sphingolipid genes predicted a unique ceramide synthase 2 (CERS2) cassette exon event for exon 8 in Luminal B breast cancer subtype generating an AS transcript that was not identified before." (PMID 33884288, 2021). "Expression of CERS2, CERS4 and CERS6 are found to be high in malignant breast tumors." (PMID 33884288, 2021). "Subtype-specific AS events in different CERS genes such as CERS2 in Luminal B subtype and CERS4 in Basal subtype suggest a strong subtype-specific post-transcriptional regulation of CERS genes that may play a role in breast cancer pathogenesis (Data set 8, 9)." (PMID 33568634, 2021). "Alternative splicing of CERS2, specifically a form lacking the main part of the catalytic TLC domain, promotes cell proliferation and migration in luminal B subtype breast cancer cells." (PMID 37958652, 2023). "Meanwhile, several other risk model genes were identified in this study (ST6GALNAC4, PLPP2, ELOVL1, HACD1, VAPB, CERS2, ALDH3B2, and HACD3) have not yet been explored in depth in breast cancer." (PMID 36059802, 2022).
bladder cancer (14 papers, 2013 to 2025). "The loss of CERS2 expression was strongly associated with progression and invasion of bladder cancer." (PMID 37627900, 2023). "Both the protein and mRNA expression of CERS2 were downregulated in advanced bladder cancer tissues and they were significantly associated with tumor stage, the depth of tumor invasion, and tumor recurrence." (PMID 37627900, 2023). "CERSs including CERS2, CERS4, and CERS6 are overexpressed in malignant breast tissues Human bladder carcinoma patients with loss of CERS2 mRNA expression have poor prognosis, and is associated with tumor progression and invasion." (PMID 33568634, 2021). "The ceramide synthase 2 (CERS2) gene has been linked to tumour recurrence and invasion in many different types of cancers including bladder cancer." (PMID 31636736, 2019). "Additionally, in the context of cancer malignancies, there are variants within the 3′ UTR of CerS2 that have been linked to bladder cancer." (PMID 37958652, 2023). "The correlation analysis was done to determine whether the expression of CERS2 was associated with bladder cancer cellular sensitivity towards NDV-mediated oncolysis." (PMID 31636736, 2019). "The cell lines used in this study were ranked based on the level of CERS2 expression and mapped to the histology, molecular subtype, genetic instability, and mutational status of classical genes associated with bladder cancer as determined and catalogued in previous studies." (PMID 31636736, 2019). "The protein expression of CERS2 was detected in bladder cancer tissues across different stages, in which it was detected in 90.5%, 62.5%, and 33.3% of stages I, II, and III tumors, respectively." (PMID 37627900, 2023). "CERS2 (also known as LASS2) mRNA expression was significantly different across four bladder cancer cell lines (EJ, EJ-M3, T24, and BIU-87 cells)." (PMID 37627900, 2023). "In this review, we focus on the influence of CERS2 in bladder cancer (BC), approaching the existing literature about its structure and activity, as well as the miRNAs regulating its expression." (PMID 37958652, 2023). "Considering these mixed findings, this review aims to uncover the role of CERS2 in bladder cancer by combining detailed molecular information, clinical studies, and datasets from transcriptomics analyses of BC patients." (PMID 37958652, 2023). "Regarding human bladder carcinoma cell lines, it has been described that the most malignant cells express lower amounts of CERS2 at both the mRNA and protein levels." (PMID 37958652, 2023). "Overexpression of CERS2 induces significant suppression in proliferation and migration of breast, prostate, and bladder cancer cells." (PMID 33568634, 2021). "A recent study found that the expression level of CerS-2 in bladder cancer samples was significantly lower than that in the corresponding normal tissues." (PMID 30988071, 2019). "The CERS2 gene was found to be differentially expressed across the different bladder cancer cell lines that were investigated in this study." (PMID 31636736, 2019). "The promigratory role of CERS2 identified in this study that contrasts previous studies in different bladder cancer cells should be further investigated to clarify the context in which the expression of CERS2 modulates the cancer cell migration phenotype." (PMID 31636736, 2019). "The CERS2 protein was differentially expressed in the bladder cancer tissues analysed, where some tumours expressed high levels while some tumours expressed none or low levels of CERS2." (PMID 31636736, 2019). "Findings from our study revealed that the CERS2 gene is differentially expressed in different types of bladder cancer cell lines." (PMID 31636736, 2019). "To date, no studies have been conducted to determine the potential of CERS2 as a biomarker that can predict NDV oncolytic response in bladder cancer." (PMID 31636736, 2019).
bladder cancer (continued). "This study demonstrates that CERS2 is differentially expressed in different types of bladder cancer cell lines and that the siRNA-mediated downregulation of the expression of CERS2 reduces the migratory potential of UMUC1 bladder cancer cells." (PMID 31636736, 2019). "The opposing roles that CERS2 plays in different types of bladder cancer cells suggest that the influence of CERS2 on the migratory potential phenotype is dependent on other factors such as the combinatorial expression of other genes." (PMID 31636736, 2019). "In this study, the expression levels of CERS2 in bladder cancer cell lines were analysed using qRT-PCR and the protein expression in clinical bladder cancer histopathological specimens were examined via immunohistochemistry." (PMID 31636736, 2019). "CERS2 knockdown was established in UMUC1 cells instead of the higher CERS2-expressing bladder cancer cell lines (UMUC10, SCaBER, UMUC3, and HT1376) because these cells were growing at a very slow rate." (PMID 31636736, 2019). "In addition, the differential mRNA expression of CERS2 was detected in freshly frozen bladder cancer tissues, paraneoplastic, and normal bladder tissues." (PMID 37627900, 2023). "Thus, further studies need to be conducted to effectively delineate the context in which the level of CERS2 affects bladder cancer cell phenotype." (PMID 31636736, 2019). "The differential CERS2 expression across the various bladder cancer cell lines in this study reflects tumour heterogeneity and that the functional significance of CERS2 expression may vary across different bladder tumours." (PMID 31636736, 2019). "Unfortunately, the potential of CERS2 as a predictive biomarker was found to be limited but may have the potential as a therapeutic target for bladder cancer, since the siRNA-mediated downregulation of CERS2 expression resulted in reduced bladder cancer cell migratory potential." (PMID 37627900, 2023). "Bladder cancer patients with negative CERS2 expression had significantly poorer survival as compared to those with positive CERS2 expression." (PMID 37627900, 2023). "The weak correlation suggests that CERS2 expression is not a suitable biomarker for predicting bladder cancer response towards NDV anticancer therapy." (PMID 31636736, 2019).
Insulin resistance (14 papers, 2015 to 2023). Increased resistance towards insulin, that is, diminished effectiveness of insulin in reducing blood glucose levels. "Mice deficient in ceramide synthase 2 are unable to synthesize very-long-chain ceramides and suffer from hepatic insulin resistance." (PMID 36077197, 2022). "One prominent example describes a compensatory up‐regulation of CerS6‐derived increase of C16:0 Cer in haplodeficient CerS2 mice, which mediated susceptibility to diet‐induced steatohepatitis and insulin resistance." (PMID 31692231, 2020). "A decrease in CerS2 activity in liver leads to compensatory increases in long-chain C16-ceramides that confers susceptibility to diet-induced steatohepatitis and insulin resistance." (PMID 26260413, 2015). "A recent study in cardiomyocytes showed that overexpression of CerS2 elevated levels of very-long-chain ceramides and caused insulin resistance, oxidative stress, mitochondrial dysfunction, and mitophagy, suggesting a similar mechanism in cardiomyocytes from patients with FRDA." (PMID 35850241, 2022). "Similarly, Raichur and colleagues observed that reductions in very‐long‐chain ceramide levels in Cers2 haploinsufficient mice were associated with increased susceptibility to lipid‐induced insulin resistance and reduced hepatic fatty acid oxidation." (PMID 31724300, 2019). "In addition, CerS2 haploinsufficiency in mice leads to compensatory increase in long-chain C16:0 ceramide that confers susceptibility to diet-induced insulin resistance and dysregulated lipid metabolism." (PMID 25993337, 2015). "Finally, it has been demonstrated that liver-specific ablation of CerS2 in mice causes hepatic insulin resistance due to reduced phosphorylation of the insulin receptor and its inability to translocate into detergent-resistant membranes." (PMID 25993337, 2015). "In a deterministic and stochastic simulator model using cultured macrophages, ceramide and S1P were shown to play a role in controlling the AKT pathway and insulin resistance via manipulating levels of ceramide synthases (CERS2, CERS5 and CERS6) and DEGS2." (PMID 32914148, 2020). "The CerS2‐null mice share similarities with the pathophysiological changes observed in patients or mouse models of diabetes mellitus, as insulin resistance and glucose intolerance were observed in CerS2‐null mice." (PMID 26288989, 2015). "On the other hand, the lack of CerS2, and the subsequent elimination of these ceramide species causes hepatic insulin resistance in mice." (PMID 28714882, 2017). "Interestingly, CerS2 (responsible for the production of very long chain ceramides) has already been shown to be important for normal liver function, as CerS2-KO mice suffered from hepatocarcinoma and hepatic insulin resistance." (PMID 35163788, 2022). "In diabetic cardiomyopathy, ceramide synthase 2 (CerS2)- and CerS5-derived ceramides, including VLC ceramides, led to increased mitophagy and insulin resistance." (PMID 33133017, 2020).
prostate carcinoma (10 papers, 2013 to 2024). A carcinoma that arises from epithelial cells of the prostate gland. "Studies found that silencing of CerS-2 gene can promote growth, proliferation, invasion, and metastasis of human PC cell both in vitro and in vivo, and CerS-2 had a low expression level in the highly metastatic prostate cancer cell line PC-3M-1E8." (PMID 30988071, 2019). "Also, tumors with down-regulation of CerS-2 tend to show more frequent lymph node metastasis, indicating that CerS-2 is a novel tumor metastasis suppressor gene for prostate cancer." (PMID 30988071, 2019). "Thus, interaction of KLF6 and Sp1, together with their binding of elements in exon 1, are critical events in the initiation of transcription of the CerS-2 gene in human prostate carcinoma cells." (PMID 30988071, 2019).
hepatocellular carcinoma (9 papers, 2015 to 2024). A malignant tumor that arises from hepatocytes. "Hepatic ceramide accumulation has previously been linked to non-invasive hepatocellular carcinoma in a ceramide synthase 2 knockout model." (PMID 31835809, 2019). "In addition, CerS2 deficiency in mice results in severe hepatopathy with an increased rate of hepatic apoptosis from ~30 days of age and progressive hepatomegaly and hepatocellular carcinoma from ~10 months of age." (PMID 25993337, 2015). "Mice that expressed a catalytically inactive mutant CerS2 developed hepatocellular carcinoma (HCC) at a young age (8 weeks), while mice that were deficient for CerS2 developed liver adenoma and HCC later in adulthood (7–10 months)." (PMID 34069611, 2021). "The activity of V-ATPase can be inhibited by ASGR1 through interacting with CerS-2, thereby suppressing the metastatic potential of hepatoma cells." (PMID 30988071, 2019).
ovarian carcinoma (8 papers, 2021 to 2024). A malignant neoplasm originating from the surface ovarian epithelium. "Metastasis-prone sublines of SKOV3 ovarian cancer cells had decreased CerS2 expression and a concomitant reduction in Cer concentrations." (PMID 38235387, 2023). "Downregulation of CerS2 induced metastasis in ovarian cancer whereas knock-in of CerS2 suppressed the formation of lamellipodia required for cancer cell motility." (PMID 38235387, 2023). "Downregulation of CerS2 in ovarian cancer cell lines stimulates in vivo metastasis and invasiveness." (PMID 35565311, 2022). "The CerS enzyme that synthesizes very-long-chain ceramides, CerS2, was reported to have an antimetastatic gene function in ovarian cancer cells." (PMID 35565311, 2022).